LGALS1 (galectin 1)
Diseases named in the same sentence as LGALS1 in open-access papers (continued):
Sharing a sentence is not in itself a finding about the gene and the disease.
tumor (continued). "Our study aimed to elucidate the role of Galectin-1 (Gal-1) role in the immunosuppressive tumor microenvironment (TME) of prostate cancer (PCa)." (PMID 38953033, 2024). "Interactions of Tim-3 with the membrane-bound or soluble CEACAM1 and/or galectin-1 produced by tumor cells led to the inhibition of NK-cell-mediated tumor cell killing independent of MHC class I status." (PMID 39457710, 2024). "Evidence from a variety of cancer types suggests that the expression of galectin-1 is frequently higher in tumor tissues in contrast with healthy or benign tissues." (PMID 38202898, 2023). "LGALS1 is mainly involved in the induction of a tolerance program, prompting immune evasion of tumor cells." (PMID 38273850, 2023). "An inhibition of Galectin-1 results in decreased tumor-cell migration, invasion, and tumor progression." (PMID 37686288, 2023). "Overall, as the final common effective tumor killer cells, cytotoxic T cells can be inhibited by multiple sources of galectin-1, thus establishing tumor immune privilege." (PMID 37047471, 2023). "FLNA, GAPDH, glutathione S-transferase P1 (GSTP1), and galectin-1 (LGALS1) were related to the I-kappaB kinase/NF-kappaB signaling pathway, which was closely related to the apoptosis process of tumor cells." (PMID 37124724, 2023). "In contrast, O-glycan-modifying sialyltransferase ST6GalNAcs reduces the binding affinity of galectins (galectin-1 and galectin-3) to the tumor cell surface, thereby inhibiting intravascular aggregation of tumor cells and consequent metastasis." (PMID 36873388, 2023). "Numerous studies have shown that galectin-1 is overexpressed in different tumours, including breast, lung, ovarian, pancreas, and prostate cancers." (PMID 37371482, 2023). "LGALS1/GAL1 and LGALS3/GAL3 are β-galactoside–binding lectins and components of the tumor-associated bulky glycocalyx that regulate the function and structure of glycoproteins." (PMID 36735782, 2023). "Galectin-1 is synthesized by different cell types in the tumor microenvironment, including macrophages, regulatory T cells, dendritic cells, myeloid-derived suppressor cells, cancer cells, endothelial cells, and fibroblasts." (PMID 36873388, 2023). "Many other studies also reported that tumor-derived galectin-1 impaired the anti-tumor properties of cytotoxic T cells." (PMID 37047471, 2023). "Blockade of immunosuppressive functions of galectin-1 induced tumor rejection, stimulating the generation of tumor-specific T-cell-associated response." (PMID 36873388, 2023). "The overall survival rate of the high–Galectin-1 expression group was markedly lower than that of the low–Galectin-1 expression group across different HCC tumor grades." (PMID 37433225, 2023). "The LGALS1 expression in the tumor groups was significantly higher than that in the normal group (p<0.001), but there was no statistical significance between the well-differentiated and poorly differentiated cSCC groups." (PMID 38099574, 2023). "In OSCC patients, the expressions of galectin-1 and galectin-3 were detected to be significantly higher than in controls, both in blood and in tumor tissues." (PMID 37445908, 2023). "Overexpression of many galectins, notably galectin-1 and galectin-3, occurs in cancerous cells and correlates with tumor progression and metastasis in some cancers." (PMID 36974238, 2023). "Previously, our group showed the apoptosis of tumor-infiltrating activated T-cells induced by galectin-1 accumulated in the tumor microenvironment." (PMID 37515069, 2023). "Meanwhile, laminin in the basement membrane, fibrin, and other glycoproteins provide the necessary epitopes for galectin-1 to cross-link with ECM and encourage galectin-1 to mediate tumor cell adhesion to the ECM." (PMID 37328752, 2023).
tumor (continued). "Galectin-1-VEGFR-2 interaction induces tumor outgrowth and limits the efficacy of anti-VEGF therapy on the endothelium." (PMID 36873388, 2023). "Differential gene expression analysis, immunohistochemistry on original tumor samples, and knock‐out experiments in zebrafish subsequently identified LGALS1 as a primary regulator of immunosuppression." (PMID 37791581, 2023). "Given the crucial role of LGALS1 in tumor immune evasion, our subsequent analysis focused on the LGALS1-PTPRC interaction, which was observed in ST tissue slices of various tumors." (PMID 37833788, 2023). "Of which, we noticed that LGALS1 showed the most significant expression difference between tumor and normal cells, thus effects of LGALS1 on KIRC cell migration and invasion ability were further explored." (PMID 38035023, 2023). "Galectin-1–expressing γδ T cells are known to suppress antigen-specific anti-tumor immunity in a TLR5-dependent manner." (PMID 36480166, 2023). "Thiodigalactoside (TDG) is a synthetic disaccharide with a high affinity for galectin-1, thereby blocking galectin-1-mediated tumor angiogenesis and immune response, and preventing oxidative stress in a non-selective manner." (PMID 36873388, 2023). "Galectin-1 is mostly detected in the stroma of the pancreas, thereby promoting tumor-stroma crosstalk in PDAC." (PMID 36873388, 2023). "In this case, we attempt to shed light on the effect of galectin-1 in infection, transplantation, tumor, and autoimmunity-related diseases." (PMID 37047471, 2023). "Consistently, knock-out of the galectin-1 gene in zebrafish and mouse models strongly impaired vascular guidance, tumor growth and angiogenesis." (PMID 36873388, 2023). "Given that the suppressive tumor microenvironment is one of the major culprits accounting for the progression of cancer, galectin-1, an immune suppressive biomarker, has received a great deal of attention." (PMID 37047471, 2023). "Galectin-1-mediated anti-tumor immunity is also regulated through its direct interactions with CD43, CD45, and CD7 receptors expressed on the surface of T cells, leading to the redistribution of glycoreceptors into segregated microdomains (46–, 48)." (PMID 36873388, 2023). "On the other hand, patients who showed the overexpression of galectin-1 in their tumour tissue had poor overall survival in the advanced-stage small-cell lung cancer." (PMID 37371482, 2023). "So, who plays a significant role in the formation of suppressive tumor immune microenvironment, tumor-derived or host-derived galectin-1?" (PMID 37047471, 2023). "Among them, Galectin-1 is involved in the regulation of cell–cell and cell–matrix interactions and multiple aspects of cancer progression and tumor biology." (PMID 37433225, 2023). "The tumour cells/implanted tumours treated with galectin-1 inhibitor OTX008 were significantly suppressed." (PMID 37371482, 2023). "Galectin-1 can influence the proliferation of CD8†T cells and the immunosuppressive capacity of CD8†CD122†PD-1†Tregs, lower Galectin-1 expression result in reduced tumor growth." (PMID 36712844, 2022). "For example, while the stroma is enriched in the expression of Galectin-1, Galectin-4 is expressed mainly by tumour cells." (PMID 35017635, 2022). "It was reported that Lgals1 can trigger an apoptotic program involving an increase of mitochondrial membrane potential and play a key role in tumor-immune escape by killing antitumor effector T-cells." (PMID 35308536, 2022). "Galectin-1 affects the interaction of tumour cells with endothelial cells, which is critical in invasion and metastasis." (PMID 34693476, 2022). "Galectin-1 and galectin-3 expression on the tumor cell membrane promotes the aggregation of homotypic tumor cells." (PMID 36382024, 2022). "Galectin-1 has a wide range of biological functions that are involved in tumor cell transformation, angiogenesis, immune evasion, sensitivity to radiotherapy, and regulation of the cell cycle, apoptosis, and inflammation." (PMID 36428567, 2022).
tumor (continued). "Galectin-1 and IL-33 share the same tumor promoting effect in CRC, by helping tumor cells in bypassing of apoptosis." (PMID 35611243, 2022). "Overexpression of tumor galectin-1 and galectin-3 were found in 26.8% and 19.5% of patients, respectively." (PMID 35280768, 2022). "Overexpression of tumor galectin-1 was the most significant prognosticator to predict worse LRPFS in both univariable (p = 0.007) and multivariable analyses (p = 0.022)." (PMID 35280768, 2022). "Galectin-1 and galectin-3 assume key roles in stabilizing immune function in addition to playing a critical role in tumor immune evasion." (PMID 36428567, 2022). "Galectin-1 and galectin-3 are highly expressed in several tumor tissues, with the former being emerged as a new target for clinical trials." (PMID 36428567, 2022). "Galectin-1 in CRC exhibits different aspects of tumor progression, such as cell adhesion, tumor cell transformation and growth." (PMID 35611243, 2022). "We also find a direct correlation between LGALS1 transcript levels and H-1PV oncolytic activity in 53 cancer cell lines from different tumour origins." (PMID 35632759, 2022). "In a top-down proteomic study based on 2D-PAGE analysis conducted on freshly frozen tissues from 14 patients, we previously identified galectin-1 as being upregulated in tumours from a therapy resistant subgroup." (PMID 35008410, 2022). "It was also demonstrated that serum galectin-1 levels reflect the tumor burden and adverse clinical characteristics of cHL." (PMID 35677161, 2022). "The expression of galectin-1 and galectin-3 on the tumor cell membrane induces homologous aggregation of tumor cells, and it confers biomimetic nanoparticles with tumor targeting ability." (PMID 36382024, 2022). "The galectin-1 promotes immune evasion of PDAC tumor cells by interacting with NK cells and inhibiting normal NK cell function." (PMID 36428567, 2022). "In the specific metabolic process of tumor cells, galectin-1 participates and facilitates metabolic reactions." (PMID 36428567, 2022). "First, the anti-tumor properties of several synthetic heterocyclic compounds able to bind galectin-1 have been evaluated." (PMID 36703969, 2022). "In this case, galectin-1 inhibition generates oxidative stress and apoptosis of tumor cells over-expressing this lectin." (PMID 36703969, 2022). "Galectin-1 is a potent prognostic indicator of tumor progression and a highly regarded therapeutic target for various pathological conditions." (PMID 34482478, 2022). "Overall, current evidence suggests that galectin-1 is involved in ESCC progression which is in line with other tumor types." (PMID 36497271, 2022). "Overexpression of tumor galectin-1 was the most significant prognosticator to predict worse LRPFS in both univariable (hazard ratio [HR] = 3.18; p = 0.007) and multivariable analyses (HR = 3.49; p = 0.022)." (PMID 35280768, 2022). "In CTCL, tumor-secreted galectin-1 inhibits the viability, proliferation, and Th1 response of non-malignant T cells and promotes the Th2 response that is conducive to tumor survival." (PMID 35677161, 2022). "Galectin-1 promotes tumor migration, invasion, and angiogenesis through epithelial-mesenchymal transition, mediates the adhesion of tumor cells, and enhances the adhesion of cells to the extracellular matrix through glycoproteins in the basement membrane." (PMID 35677161, 2022). "Galectin-1 and galectin-3 are important contributors to the regulation of immune function and have a unique dual role in tumor regulation." (PMID 36428567, 2022). "Galectin-1 also accelerates the growth of tumor cells by promoting angiogenesis and the activation and proliferation of vascular endothelial cells." (PMID 35677161, 2022). "It has also been reported that galectin-1 knockdown promotes cisplatin sensitivity in other tumor cells, such as bulky squamous cervical cancer and epithelial ovarian cancer." (PMID 35327655, 2022).
tumor (continued). "In vitro and mice model studies have shown that galectin-1 promotes tumor cells’ migratory capability and invasiveness through modification of cytoskeleton and small GTPases." (PMID 35682991, 2022). "Western blot analysis indicated that CD47, galectin-1, and galectin-3 were detected on both the biomimetic nanoparticles and tumor cell membrane." (PMID 36382024, 2022). "In humans, galectin-1 is attached to the surface of exosomes derived from placental mesenchymal stromal cells, tumour or syncytiotrophoblast cells and is involved in exosome adhesion." (PMID 36526668, 2022). "Previous studies showed that galectin-1 was regulated by hypoxia, and tumor hypoxia is well-known to be related to resistance to radiotherapy or chemotherapy." (PMID 34201887, 2021). "In head and neck cancer, high galectin-1 expression upregulated PD-L1 expression on the tumour epithelium reducing T-cell infiltration into the tumour." (PMID 34771746, 2021). "We previously revealed the immunoregulatory role of galectin-1 in causing the apoptosis of activated T-cells, and we identified galectin-1 protein as a master regulator in the promotion of tumor vascularization." (PMID 34209651, 2021). "Compelling evidence supports the immunosuppressive role of galectin-1 in different tumor types and its ability to promote tumor-immune escape." (PMID 35008740, 2021). "We previously found that LYAR was expressed at a higher level in metastatic CRC tissues and that it promotes tumor cell migration and invasion by upregulating LGALS1 expression in CRC cell lines." (PMID 35069968, 2021). "LGALS1 covers various biological functions depending on its cellular location, e.g. when expressed intracellularly, LGALS1 contributes to tumor progression via immune suppression, angiogenesis and metastasis." (PMID 33690729, 2021). "We have made significant contributions in deciphering the role of the immunoregulator galectin-1 (Gal-1) in tumor-immune escape mechanisms." (PMID 35008313, 2021). "In gingival squamous carcinoma (GSCC), high galectin-1 expression in tumour tissue correlated with decreased infiltration and increased apoptosis of CD8+ T-cells." (PMID 34771746, 2021). "Proteomic analysis revealed reduced tumor secretion of inflammatory factors Galectin-1, Osteopontin, CCL5, and CCL9 upon treatment with Ocoxin." (PMID 33669949, 2021). "LGALS1 mainly participated in inducing tolerogenic programs and contributed to tumor cell immune evasion." (PMID 35127715, 2021). "Collectively, these studies demonstrated that tumor-derived galectin-1 impacts both innate and adaptive arms of antitumor immune responses." (PMID 35008740, 2021). "In the tumor microenvironment, galectin-1 has been shown to be involved in immune suppression, tumor angiogenesis and metastasis." (PMID 34201887, 2021). "The predictive value of LGALS1 for tumor prognosis has been widely researched in multiple types of cancer." (PMID 33854625, 2021). "The study highlights the clinical significance of serum Galectin-1 as a suitable noninvasive biomarker for the early detection of the OC, monitoring response to treatment and an indicator of tumour metastasis and invasion." (PMID 34556165, 2021). "In this regard, in an in vivo setting, silencing galectin-1 by an intranasal knockdown strategy resulted in reduced tumor Ki67 staining, indicating diminished proliferation rates than untreated tumors." (PMID 35008740, 2021). "In this paper, we demonstrate that tumor activated fibroblasts overexpress Galectin-1 (Gal-1) and consequently release MVs containing increased levels of this protein." (PMID 34021474, 2021). "Galectin-1 and galectin-3 are significantly upregulated in BCa compared with normal cells and contribute to tumor growth and invasion." (PMID 32005776, 2020).
tumor (continued). "Secretion of different soluble factors, such as transforming growth factor-β (TGF-β), and galectin-1 by tumor cells, directly inhibit T cell function, leading to decreased tumor killing." (PMID 32983125, 2020). "Galectin-1 is known to enhance tumor angiogenesis through inhibiting T cell-mediated cytotoxic immune responses." (PMID 32785175, 2020). "CS nanocapsules carrying EGFR and galectin-1 siRNA significantly increased survival in tumor-bearing mice and decreased gene expression in tumor tissue." (PMID 32849207, 2020). "Enhanced tumor growth was observed in both models, proving the inhibitory effect galectin-1 has on NK cell anti-tumor function." (PMID 32063906, 2020). "Monoclonal anti-galectin-1 antibody (F8.G7) was shown to decrease tumor angiogenesis and promote tumor regression in a mouse model of Kaposi’s sarcoma." (PMID 32486344, 2020). "Such a galactose dendritic molecule allows high affinity to tumor cells due to the ability of galectin-1 to establish multivalent interactions with the galactose units of the dendritic unit." (PMID 32005776, 2020). "Porphyrinoids attached to the galactodendritic unit 4 have demonstrated in previous studies the ability to target galactose-binding proteins, such as galectin-1, overexpressed in tumor tissues." (PMID 32005776, 2020). "Its interaction with galectin 1 and galectin 3 leads to tumor cell aggregation and promotes cancer metastasis and T-cell apoptosis in epithelial tissue." (PMID 32367478, 2020). "Mechanistically, galectin-1 prevented T-cell infiltration into the tumour through up-regulation of immune checkpoint molecules on the tumour endothelium." (PMID 33187209, 2020). "It was reported that DCs with abnormal function in the tumor microenvironment can produce tumor promoting IL-6 and immunosuppressive galectin-1, which can impair the local anti-tumor immunity." (PMID 33240930, 2020). "Other mediators such as galectin-1 and -9 in tumor-derived EVs were also found to induce T-cell apoptosis and immune suppression within the tumor." (PMID 32150875, 2020). "We observed an enhanced tumour development in gal-1−/− mice compared to wild-type mice, suggesting that galectin-1 has a functional role in stromal cells in myeloma microenvironment." (PMID 30813402, 2019). "Tumour cells in the galectin-1-rich environments express genes important for tumour progression such as SPIN1, FUSIP1, TRIM23, PTPLAD1, MAP3K2." (PMID 30925774, 2019). "Our results showed that FAM289 and Galectin-1 interdependently regulates tumor proliferation, migration and invasion." (PMID 31492191, 2019). "Galectin-1 is abundant in most organs: muscle, heart, liver, prostate, lymph nodes, spleen, thymus, placenta, testis, retina, macrophages, B-cells, T-cells, tumours." (PMID 31652641, 2019). "Galectin 1 (Gal-1) is a protein that is over-expressed in GBM and is highly associated with tumor progression." (PMID 31779126, 2019). "In an ovarian cancer model, tumor-driven Satb1 overexpression in terminally differentiated DCs results in a tolerant, pro-inflammatory state as evidenced by the secretion of Galectin-1 and IL-6, promoting tumor growth and immune evasion." (PMID 31921140, 2019). "In order to explore the mechanisms underlying FAM289-mediated tumor progression, we identified the FAM289 protein interacting with galectin-1 protein." (PMID 31492191, 2019). "Galectin-1 (Gal-1) is a 14 kDa protein that has been well characterized for promoting cancer metastasis and tumor immune evasion." (PMID 31387209, 2019). "In fact, NT cells treated with IL-10 produced tumor activator factors such as RhoA, the glia maturation factor beta, galectin-1, the isocitrate dehydrogenase subunit alpha, and the D-3-phosphoglycerate dehydrogenase." (PMID 31766635, 2019). "In this complex scenario, galectin-1 and galectin-3 deserve consideration for the functional implications they can have on tumor immune response." (PMID 30935099, 2019).